PKD2 (polycystin 2, transient receptor potential cation channel)
Diseases named in the same sentence as PKD2 in open-access papers (continued):
Sharing a sentence is not in itself a finding about the gene and the disease.
cyst (123 papers, 2008 to 2026). A sac-like closed membranous structure that may be empty or contain fluid or amorphous material. "PKD1 truncating mutations are associated with earlier onset of kidney failure, faster cyst expansion, and higher total kidney volume, whereas PKD2 variants generally produce a milder disease course with slower progression." (PMID 41597516, 2026). "The association between GPCRs located on primary cilia and the polycystin proteins, PC1 and PC2, is crucial for regulating calcium signaling in primary cilia, and mutations in Pkd1 or Pkd2 disrupt this complex, promoting cyst formation and kidney dysfunction." (PMID 40801635, 2025). "Site-specific gene editing techniques, such as CRISPR/Cas9, are commonly employed to generate homozygous or heterozygous mutations in PKD1 or PKD2, thereby modeling the genetic basis of cyst formation." (PMID 40002937, 2025). "Renal tubular cells of individuals carrying PKD1 or PKD2 mutations are likely more susceptible to DNA damage and aberrant apoptosis, which in turn facilitates spontaneous, cyst-initiating “second-hit” mutations in genes that include PKD1 and PKD2." (PMID 38474184, 2024). "Initiation of cyst formation in ADPKD is attributed to functional inactivation of polycystin-1 or -2 due to a PKD1 or PKD2 mutation." (PMID 38474184, 2024). "There are fewer and shorter cilia in renal epithelial cells of PKD2-deficient mice, while the cilia of PKD2-deficient cyst-lining tubule cells are longer than the control group from another report." (PMID 39451240, 2024). "With these previous studies and pitfalls in mind, we set out to identify potential cyst drivers by controlling the timing of Pkd2 loss." (PMID 39666736, 2024). "In juvenile kidneys, CD206+ R2 cells are already present, and induction of the Pkd2 mutation leads to rapid cyst progression." (PMID 36457161, 2023). "The tubular cells of nephron-like kidney organoids derived from hPSCs carrying biallelic loss-of-function mutations in PKD1 or PKD2 display cyst formation." (PMID 37146581, 2023). "Two proteins encoded by PKD1 and PKD2, polycystin-1 and polycystin-2, are involved in cyst formation." (PMID 37241147, 2023). "Collectively, these data suggest that CX3CR1+ macrophages, and a CD206+ subset of these macrophages, are closely associated with cyst formation in the adult-induced Pkd2 mutants." (PMID 36457161, 2023). "Our recent work showed that Pkd2 loss activates JNK signaling and that genetic reduction of JNK activity reduced cyst growth triggered by loss of Pkd2." (PMID 35253003, 2022). "We recently found that the stress-activated mitogen-activated protein kinase (MAPK) pathway c-Jun N-terminal kinase (JNK) pathway is activated in cystic disease and genetically removing JNK reduces cyst growth driven by a loss of Pkd2." (PMID 35253003, 2022). "The suppression of cyst growth by the loss of cilia was found to occur in all segments of the renal tubules following both early and late Pkd1 or Pkd2 gene deletion." (PMID 35832738, 2022). "To distinguish these possibilities, we tested how JNK inhibition affects cyst formation driven by Pkd2 loss." (PMID 34962918, 2021). "Relevant to this study is that, mirroring the ADPKD cyst inflation process, pkd2 knockdown causes a significant increase in CFTR-mediated fluid secretion into the KV lumen." (PMID 34445719, 2021). "ADPKD is caused by mutations in PKD1 (polycystin 1) or PKD2 (polycystin 2), but the underlying complex molecular events leading to continuous cyst growth are still poorly understood." (PMID 32185407, 2020). "Remarkably, we found several somatic mutations in genes other than PKD1 or PKD2, ranging from 3 to 15 mutations per cyst." (PMID 32163234, 2020). "ADPKD is caused by mutations in either PKD1 or PKD2 genes, where disruption of their normal functions leads to excessive proliferation of the renal tubular epithelium causing cyst formation." (PMID 31515477, 2019).
cyst (continued). "In this study, we investigated miRNA profiles associated with severity of cyst development in the ADPKD models of Pkd1 or Pkd2 conditional knockout mice." (PMID 29074972, 2017). "Loss-of-function mutations in either PKD1 or PKD2 or reduced levels of functional protein are causative for cyst formation, but the mechanisms behind this process are still poorly understood." (PMID 28644734, 2017). "Trichostatin A (TSA), a histone deacetylase inhibitor, was found to inhibit cyst formation in pkd2-deficient zebrafish and Pkd2–/– mouse embryos." (PMID 28197487, 2015). "Mutations of PKD1 and PKD2 induce cyst formation in the kidney, and cyst formation in part arises because of derestricted cell proliferation." (PMID 26579493, 2015). "Functional loss of the gene products of PKD1 and PKD2, polycystin 1 and polycystin 2, leads to abnormalities in a variety of intracellular signaling pathways, which contribute to cyst initiation and expansion." (PMID 26110849, 2015). "While not affecting cell proliferation which is a marked difference to the renal cyst formation, we demonstrate that pkd2-knockdown causes a significant increase in the CFTR-mediated fluid-secretion into the KV lumen mirroring the cyst inflation process." (PMID 26432887, 2015). "It is caused by mutations in the PKD1 and PKD2 genes, and manifests as progressive cyst growth and renal enlargement, resulting in renal failure." (PMID 25491204, 2014). "This common, yet complex, genetic renal disease occurs in response to mutations in either the PKD1 or PKD2 gene, and is characterized by progressive cyst enlargement due to excess fluid secretion and proliferation of renal tubular epithelial cells." (PMID 24098285, 2013). "In contrast mutations in Pkd1 and Pkd2 do result in cyst formation despite normal oriented cell division, suggesting that loss of PCP-related oriented cell division is not sufficient to generate kidney cysts." (PMID 23351924, 2012). "In human polycystic kidney disease, patients are heterozygous for either PKD1 or PKD2 mutations and suffer from cyst formation and eventual kidney failure." (PMID 18454189, 2008). "This led to the formation of the “two-hit” hypothesis, which states that cyst initiation occurs when the normal allele of either PKD1 or PKD2 undergoes a mutation, as those tubular epithelial cells become dysfunctional and gain a growth advantage." (PMID 40722835, 2025). "According to the genetic mechanism proposed in ADPKD of a “two hit” event, by which there is a somatic inactivation of the remaining wildtype allele, cellular PKD1/PKD2 functional activity may fall below a critical threshold, and cyst initiation ensues." (PMID 39940890, 2025). "These include transcriptional and translational regulators of PKD1/PKD2, modifier genes (e.g., cyst formation, type IV collagen), and genetic variants linked to chronic kidney disease (CKD) risk factors such as obesity, dyslipidemia, hypertension, and diabetes." (PMID 40051696, 2025). "While in the pancreas, detecting even a single cyst determines the probability of PKD1 versus PKD2 mutation, nearly all ADPKD subjects have liver cysts; the critical information is total liver cyst volume and liver cyst fraction, which are not substantially affected by missing small cysts." (PMID 39058059, 2024). "To determine whether CD206+ R2 macrophages are associated with the rapid stage of cyst formation in adult-induced Pkd2 mutants, we analyzed CD206+ R2 with flow cytometry and IF microscopy at 16 wpi." (PMID 36457161, 2023). "Pkd2 loss led to rapid cyst formation along with increased JNK and c-Jun phosphorylation." (PMID 35253003, 2022). "Finally, we demonstrate that PKD1 or PKD2 derepression reverses cyst-pathogenic events in primary kidney cyst epithelia derived from individuals with ADPKD." (PMID 35965273, 2022). "We performed PKD1 and PKD2 mutation analysis using DNA from cyst cells." (PMID 35965273, 2022).
cyst (continued). "Therefore, NS398 inhibited cyst growth in both Pkd2 zebrafish and early‐onset Pkd1‐deficient mouse models and improved the renal function in early‐onset Pkd1‐deficient mouse model." (PMID 34551202, 2021). "Within hours of inactivation of Pkd2 and loss of polycystin-2, we observed significant progression in tubuloid to cyst morphology that correlated with 35 differentially expressed genes, many related to cell junctions, matrix interactions, and cell morphology previously implicated in cystogenesis." (PMID 32513820, 2020). "The second question is while anti-miR-17 treatment slows cyst growth caused due to Pkd2 mutations whether it will have similar beneficial effects in the setting of Pkd1 mutations is not known." (PMID 30760828, 2019). "However, Pkd1 or Pkd2 conditional knockout mice, which are kidney-specifically deficient, are born normally and show rapid cyst formation from postnatal day 1 (P1), accompanied by increased cell proliferation by abnormal activation of the MAPK/ERK pathway." (PMID 29074972, 2017). "This difference may be related to their phenotypic differences: even though these two models showed similar cyst progression and timing of renal failure, Pkd2-deficient mice remained alive longer than Pkd1-deficient mice, for maximum of about 20 days." (PMID 29074972, 2017). "Mutations in PKD1 and PKD2 cause cyst formation through unknown mechanisms." (PMID 34301992, 2021). "PKD1 truncating variants are associated with earlier onset of kidney failure and more rapid cyst expansion, whereas non truncating PKD1 variants and PKD2 mutations generally follow a slower course." (PMID 41597516, 2026). "TNF-α can interfere with the localization of PC2 to both the plasma membrane and primary cilia by inducing the scaffold protein RAB11 family interacting protein 2 (FIP2), which in turn facilitates cyst formation in organ cultures and Pkd2 mutant mice." (PMID 41431718, 2026). "CRISPR-Cas9 technology was employed to knock out the PKD1 or PKD2 genes in these tubuloids, followed by drug treatments to induce cyst formation." (PMID 40002937, 2025). "In PKD1 or PKD2 mutant organoids, single-cell sequencing can identify cell populations including cyst wall epithelial cells, fibroblasts, and endothelial cells." (PMID 41359105, 2025). "By tracking cyst growth, researchers can correlate cyst characteristics with specific genetic mutations (e.g., PKD1 or PKD2) to better understand the disease’s underlying mechanisms, thereby facilitating the study of genotype–phenotype correlations." (PMID 41303287, 2025). "DNA methylation is known to silence gene expression and has been implicated in the downregulation of key cyst-suppressing genes, such as PKD1 and PKD2, which are essential for maintaining renal tubular cell integrity." (PMID 40801635, 2025). "For example, organoids with gene edits targeting polycystin-1 transient receptor potential channel interacting (PKD1/PC1) and polycystin-2 transient receptor potential cation channel (PKD2/PC2) can simulate cyst formation and related disease characteristics." (PMID 41359105, 2025). "In a mouse model permissive to the inactivation of Pkd1 or Pkd2 as well as subsequent gene reactivation, it was discovered that cyst formation is reversible, with cystic structures returning to normal nephrons." (PMID 39940890, 2025). "As recently reported for a mouse model enabling both inactivation of Pkd1 or Pkd2 and subsequent gene reactivation, it was discovered that cyst formation is indeed (and somehow surprisingly) reversible." (PMID 39940890, 2025). "Recently, anoctamin 1 (ANO1, also known as TMEM16A) has been identified as a Ca2+-activated Cl- channel that promotes fluid secretion in PKD1 or PKD2 knockout models, and its pharmacological inhibition slows cyst growth in cell cultures, as well as in mice." (PMID 40722835, 2025).
cyst (continued). "Mutations in the PKD1/PKD2, which are responsible for ADPKD, affect intracellular signaling, including the mammalian target of the rapamycin (mTOR) pathway, leading to cyst formation and progression, while NF1 mutations overactivate the Ras proteins." (PMID 40051696, 2025). "For example, the zebrafish pronephros consists of only two nephrons with a shared glomerulus and the pkd2 zebrafish model only forms one large cyst, in contrast to the more complex microenvironment of early cystic and non‐cystic tissue in iKsp‐Pkd1−/− mice." (PMID 38561249, 2024). "To identify genes with the potential to promote cyst initiation, we deleted polycystin-2 (Pkd2) in mice and surveyed transcriptional changes before and immediately after cysts developed." (PMID 39666736, 2024). "The interaction between the PKD1 and PKD2 gene products, polycystin-1 and polycys-tin-2, forms a complex involved in calcium signaling, which is crucial for tubular structure maintenance and cyst development." (PMID 39451240, 2024). "MRTF-A mRNA expression was greatly upregulated in the dilated tubules, the adjacent stroma, and the cyst-lining epithelium of the PKD2 kidneys, contrasting the minimal expression in the normal tubules of the same animals and the control kidneys." (PMID 38891116, 2024). "Inactivation of Glis2 in early onset and adult mouse models of Pkd1 and Pkd2 resulted in suppression of cyst formation." (PMID 38693102, 2024). "Over-proliferation of renal tubular epithelial cells occurs in both heterozygous and homozygous Pkd2 mutant mice before cyst formation." (PMID 39451240, 2024). "Despite differing mechanisms from Pkd1 and Pkd2 mutations in ADPKD, PKHD1 mutations similarly disrupt renal cell signaling and structural integrity, leading to cyst formation primarily in the collecting ducts of the kidneys and often affecting the liver." (PMID 39802450, 2024). "This compound has been shown to increase Pkd1/Pkd2 expression and reduce cyst growth in CRISPR-edited cellular and mouse models of ADPKD." (PMID 39595570, 2024). "This is in contrast to the significantly smaller cyst size in pkd2 knockdown zebrafish following BB‐FCF treatment compared to vehicle treatment." (PMID 38561249, 2024). "Recent studies indicate that intact cilia promote cyst formation in PKD2-mutant kidneys, challenging the current theory that PKD2 functions through cilia in the kidneys." (PMID 39451240, 2024). "The drug was able to preferentially distribute in cysts in the kidney and collecting ducts, inhibiting miR-17 targets including Pkd1 and Pkd2 and effectively controlling cyst growth." (PMID 39802450, 2024). "Using Cx3cr1 null mice, we reduced macrophage number, including CD206+ macrophages, and showed that this significantly reduced cyst severity in adult-induced Pkd2 mutant kidneys." (PMID 36457161, 2023). "In contrast to the rapid cyst formation that occurs in the P2- or P7-induced Pkd2 mutants, only tubule dilations were observed at 6 wpi in adult-induced Pkd2 mutant kidneys." (PMID 36457161, 2023). "Although rapid cyst formation occurred in both juvenile-induced Pkd2 mutant mice, there was a more aggressive and severe cystic phenotype in P2-induced Pkd2 mutant kidneys than in P7-induced Pkd2 mutant kidneys." (PMID 36457161, 2023). "The molecular changes in the interaction between PKD1 and PKD2 genes increase cell proliferation and fluid secretion, mechanisms at the basis of cyst formation." (PMID 37372416, 2023). "Pkd2 was disrupted in mice at 8 weeks of age (adult-induced model), and cyst formation and progression were examined at 6, 12 and 16 wpi." (PMID 36457161, 2023). "This change correlates with the transition from rapid to slow cyst formation in the juvenile- and adult-induced Pkd2 mutant models." (PMID 36457161, 2023).
cyst (continued). "In contrast, normal adult kidneys have very few CD206+ R2 macrophages, and loss of Pkd2 in adult-induced mice results in cyst formation in a slow and focal manner, and the CD206+ R2 macrophages only accumulate in areas of focal cyst formation." (PMID 36457161, 2023). "In Pkd2-deficient mice, the reduction of HDAC5 inhibits cyst formation by enhancing MEF2C-dependent transcription." (PMID 37878054, 2023). "This suggests two stages of cyst formation in adult-induced Pkd2 mutant kidneys: a slow focal cyst initiation stage involving proximal tubules, followed by a more rapid cyst progression phase involving DBA+ tubules." (PMID 36457161, 2023). "In another study, the HDAC class I and II deacetylase inhibitor trichostatin A (TSA), and the Class I HDAC inhibitor, valproic acid, were found to effectively reduce cyst formation, body curvature and laterality in Pkd2 mutant zebra fish morphants." (PMID 35847973, 2022). "The evidence linking Pkd1 and Pkd2 to JNK/AP-1 activity led us to ask what role JNK signaling plays in cyst formation and disease progression downstream of polycystin mutations." (PMID 35253003, 2022). "Altered Ca2+ signaling due to dysfunction of PKD1 or PKD2 is thought to initiate cyst formation in ADPKD but the mechanism of pathogenesis remains elusive." (PMID 36035467, 2022). "Consistently, we observed that compared to Pkd1RC/-; Pkd2+/+ kidneys, Pkd1RC/-; Pkd2∆17/∆17 kidneys exhibited reduced c-Myc and Yap1 expression and lower cyst proliferation and interstitial inflammation." (PMID 35965273, 2022). "This study further showed that over-expressed TACAN aggravates the tail curling and pronephric cyst formation in larval zebrafish due to PKD2 knockdown by means of CRISPR/Cas9, presumably through repressing the PKD2 channel function." (PMID 36035467, 2022). "In Pkd2–/– mice aged to allow for cyst formation, chronic administration of an oral dopamine antagonist slowed renal cyst formation; this did not occur in Pkd1–/–, which retained intact GTB in the precystic state." (PMID 33886508, 2021). "Because pools of cellular PC1 and PC2 interact at the cilium, primary cilia dysfunction has been linked to cyst formation in human and murine PKD1 or PKD2-dependent ADPKD." (PMID 33920158, 2021). "In Pkd1 and Pkd2 knock out mice, miR-21 also targets tumor suppressor programmed cell death 4 (Pdcd4) mRNA to stimulate cyst formation." (PMID 33920158, 2021). "PKD2-/- kidney organoids and matched isogenic controls were treated with tubacin (0.2–1 μM) for 48 hr and cyst size was evaluated." (PMID 34250905, 2021). "We investigated the flow-dependent PT transport in 3 major polycystic kidney disease (PKD) and ciliopathy animal models of Pkd1-, Pkd2-, and Kif3a-KO mice after gene KO but prior to cyst formation." (PMID 33886508, 2021). "In the kidneys, the Pkd2 gene is most strongly expressed in the collecting ducts, which correlates with the site of cyst formation." (PMID 34345895, 2021). "Then, by knocking down the PKD1 or PKD2 genes, these investigators observed cyst formation from kidney tubules." (PMID 34339420, 2021). "These are the results that would be expected if swings in intratubular pressure played a pathophysiological role in cyst formation of Pkd2." (PMID 33886508, 2021). "This miRNA drives cyst epithelial proliferation and inhibits the post-transcriptional expression of Pkd1, Pkd2, and hepatocyte nuclear factor 1β (Hnf-1β)." (PMID 34901057, 2021). "From the PKIS library, we identified several ALK5 kinase inhibitors as strong suppressors of the pkd2 tail phenotype and in vitro cyst expansion." (PMID 31919453, 2020). "Using the 3D tubuloid model with an inducible Pkd2 knockout system allowed the tracking of morphological, protein, and genetic changes during cyst formation." (PMID 32513820, 2020).